SHCBP1 (SHC binding and spindle associated 1)
Diseases named in the same sentence as SHCBP1 in open-access papers (continued):
Sharing a sentence is not in itself a finding about the gene and the disease.
tumor (continued). "Most importantly, the in vivo data demonstrated that silencing of SHCBP1 could significantly prohibit xenograft tumor growth in mouse model." (PMID 27572315, 2016). "The MAPK/ERK and PI3K/AKT/mTOR signaling pathways may be first stimulated by the elevated expression of SHCBP1, which leads to increased tumor growth potential." (PMID 27572315, 2016). "In support of this notion, elevated protein levels of Smyd3, H3K4me3, and Shcbp1, and p-Mek, and p-Erk and Kras were detected in tumor tissues with OE-Smyd3, but these protein levels were significantly decreased in tumor tissues expressing sgSmyd3 or OE-Smyd3/sgShcbp1." (PMID 40157910, 2025). "Similarly, SHCBP1 expression in tumour cells increased after docetaxel (DTX) exposure." (PMID 38365687, 2024). "In addition, whether targeting SHCBP1 could improve the anti-tumour effects of current chemotherapy strategies in NSCLC remains largely unknown." (PMID 38365687, 2024). "Therefore, SHCBP1 knockdown increased the tendency for aberrant mitosis which may be responsible for tumour growth inhibition." (PMID 38365687, 2024). "An increasing number of studies suggest that compromising the G2–M checkpoint may allow enhanced genotoxic drug therapy, prompting us to explore the synergistic tumour-killing effects of targeting SHCBP1 combined with low-dose DNA-damaging agents in vitro and in vivo." (PMID 38365687, 2024). "Out of these, A549 showed the most significant apoptosis and a more obvious phenomenon in senescence, indicating that tumour cells with low SHCBP1 expression were more sensitive to SHCBP1 intervention, but the different residual SHCBP1 levels after knockdown may also account for this phenomenon." (PMID 38365687, 2024). "Moreover, we suggest that tumours with lower SHCBP1 expression are more sensitive to DNA-damaging agents, which may aid in the selection of chemotherapeutic agents in clinical practice." (PMID 38365687, 2024). "However, SHCBP1 knockdown combined with tubulin-toxic drugs weakened the killing effect of the drugs on tumour cells, which may guide the choice of chemotherapeutic agents in clinical practice." (PMID 38365687, 2024). "Therefore, targeting SHCBP1 in tumour cells could abrogate the G2–M checkpoint by inhibiting the WEE1-pCDK1 (Tyr15) axis." (PMID 38365687, 2024). "Therefore, SHCBP1 may maintain the functions of tumour cell centrosomes and spindles by regulating NEK7 expression." (PMID 38365687, 2024). "Moreover, higher nuclear SHCBP1 was detected in NSCLC cells cultured in serum-free medium than in serum-containing medium, as well as in CD44/ EpCAM double-positive cells compared to the corresponding parental tumor cells, suggesting an important role of nuclear SHCBP1 in CSCs regulation." (PMID 30177836, 2019). "The expression of MELK and SHCBP1 was then evaluated in the GSE118897 and TCGA-STAD datasets, and the findings demonstrated that both genes were markedly overexpressed in tumor tissues." (PMID 40657397, 2025). "SHCBP1 IF staining of tumor tissues demonstrated that TFBG and trastuzumab combination effectively blocked SHCBP1 nuclear translocation." (PMID 33990570, 2021). "SHCBP1, KIF4A, and ECT2 have been reported to mediate tumor initiation and progression of human HCC." (PMID 31392101, 2019). "Schematics summarizing the interaction between SHCBP1 and PLK1, which promotes the Aurora A‐PLK1 interaction, leading to altered phosphorylation of PLK1 at T210, thus promoting cell mitosis and contributing to tumor development via the SHCBP1‐PLK1‐CDC25C axis." (PMID 39949984, 2025). "The data revealed that disruption of either SMYD3 or SHCBP1 in MDA-MB-231 cells did not affect cell growth in vitro but significantly inhibited tumor growth in both 231 and HCC1937 mice models with reversed the splenomegaly phenotype." (PMID 40157910, 2025).
tumor (continued). "Furthermore, SHCBP1 downregulates the expression of CXCL2, a chemokine important for neutrophil recruitment and resolution of inflammation, thereby supporting tumor cell proliferation through activation of AKT and ERK signaling and suppression of p21 and p27." (PMID 41009347, 2025). "Given that the disruption of either Smyd3 or Shcbp1 could inhibit the tumor outgrowth, we hypothesized that SMYD3-SHCBP1 signaling might shape TIME benefiting tumor growth." (PMID 40157910, 2025). "Moreover, SHCBP1, PLK1, and PHH3 (Ser10) expression in tumour cells gradually increased with increasing paclitaxel concentration, further demonstrating higher SHCBP1 expression in M phase." (PMID 38365687, 2024). "The ability of SHC SH2 domain-binding protein 1 (SHCBP1) to induce cell cycle disturbance and inhibit tumour growth has been increasingly studied, but its dynamic role in the tumour cell cycle and corresponding effects leading to mitotic catastrophe and DNA damage have rarely been studied." (PMID 38365687, 2024). "Our previous data showed that SHCBP1 knockdown led to early M-phase entry by downregulating WEE1 expression and subsequently reducing CDK1 phosphorylation at Tyr15, resulting in the abrogation of the G2–M checkpoint in tumour cells." (PMID 38365687, 2024). "SHCBP1, as an important upstream protein of the ERK1/2 signaling pathway, may be involved in the process of polyphenols inhibiting tumor cell proliferation." (PMID 38005336, 2023). "Our findings disclose that SHCBP1 is a novel downstream target gene of SS18-SSX1, and demonstrate that the oncogene SS18-SSX1 promotes tumorigenesis by increasing the expression of SHCBP1, which normally acts as a tumor promoting factor." (PMID 27572315, 2016). "While no SHCBP1-specific inhibitors have yet been implemented clinically, preclinical investigations utilizing genetic and pharmacological interventions have demonstrated that targeting SHCBP1 can suppress tumor growth and improve treatment outcomes." (PMID 41009347, 2025). "Furthermore, as the RTK binding protein Shc1 is established to mediate angiogenesis via VEGF-A-dependent signaling and SHCBP1 interacts with phosphorylated SHC1, the SHC–SHCBP1 axis may indirectly facilitate vascular remodeling in tumor contexts." (PMID 41009347, 2025). "Moreover, the DEPs in cluster 6 showed an increased trend in ferroptosis after SHCBP1 knockdown, a trend that was more obvious after the combination of SHCBP1 knockdown and ETOP administration, suggesting another effective factor contributing to tumour lethality." (PMID 38365687, 2024). "In addition, SHCBP1 inhibition in the in vivo A549 subcutaneous xenograft and the tail-vein injected LLC metastasis mouse models also remarkably attenuated tumour growth." (PMID 38365687, 2024). "Interestingly, five genes (CDC45, KIF13B, ORC6, SHCBP1,and CAPN8) were not present in previously reported molecular tumor grading signatures." (PMID 26474389, 2015). "However, we only observed the physical interaction of SHCBP1 with RACGAP1 and MKLP1, but not with PLK1 in asynchronous tumour cells, suggesting that SHCBP1 may only interact with PLK1 in the mitotic phase." (PMID 38365687, 2024).
SHCBP1 also shares sentences with these, for which no sentence is quoted: colon cancer (2 papers); esophageal squamous cell carcinoma (2); acute myeloid leukemia (1); adrenocortical carcinoma (1); bladder urothelial carcinoma (1); colon adenocarcinoma (1); COVID-19 (1); diffuse large B-cell lymphoma (1); endocervical adenocarcinoma (1); infection (1); invasive ductal carcinoma (1); liposarcoma (1); liver cancer (1); lymph node metastasis (1); lymphoid neoplasm (1); nasopharyngeal carcinoma (1); osteosarcoma (1); ovarian serous cystadenocarcinoma (1); pancreatic adenocarcinoma (1); papillary thyroid carcinoma (1); pheochromocytoma (1); sarcoma (1); skin cutaneous melanoma (1); small cell lung carcinoma (1); testicular germ cell tumor (1); thymoma (1); triple-negative breast carcinoma (1); uterine carcinosarcoma (1).